EZR (ezrin)
Diseases named in the same sentence as EZR in open-access papers (continued):
Sharing a sentence is not in itself a finding about the gene and the disease.
cholestasis (2 papers, 2023 to 2025). Impairment of the bile flow caused by obstruction within the liver, or outside the liver in the bile duct system. "A previous study of MRP2 revealed that PKC is activated during cholestasis and results in the phosphorylation of ezrin, which causes the internalization and degradation of MRP2." (PMID 40723305, 2025). "Our data on the Ezrin function in hepatocytes suggests this as the primary mechanism for the occurrence of cholestasis described in the global Ezrin knockdown mice." (PMID 37928027, 2023). "Ezrin can contribute to cholestasis in cholangiocytes, as it localizes cystic fibrosis transmembrane conductance regulator and aquaporin 1, crucial for bile fluidity and alkalinity, at the apical membrane." (PMID 37928027, 2023). "To check for Ezrin-mediated effects on the canalicular membrane constitution in cholestasis, we stained liver tissue obtained from Ezrko/ko and B6 mice after surgery for Mrp2 and Radixin as well as pERM and Radixin." (PMID 37928027, 2023). "In cholestatic diseases, changes in Radixin, but not Ezrin, activation are associated with canalicular remodeling, one of the major driving forces of cholestasis." (PMID 37928027, 2023). "Two opposing functions have been described, with activated Radixin stabilizing MRP2 at the canalicular membrane of hepatocytes, whereas activated Ezrin removes MRP2 from the membrane, promoting cholestasis." (PMID 37928027, 2023). "Our data suggest no function for Ezrin in hepatocytes during liver development, normal liver function, or cholestasis." (PMID 37928027, 2023). "Considering the Ezrin function in hepatocytes described by others, additional hepatocellular contribution to the molecular basis of cholestasis in Vil2KD/KD mice still has not been conceptualized." (PMID 37928027, 2023). "Homeostasis of the canalicular pole in hepatocytes is maintained exclusively by Radixin but not Ezrin, and Radixin dysfunction promotes cholestasis." (PMID 37928027, 2023). "We demonstrated the absence of Ezrin in hepatocytes during health and cholestasis, leaving Radixin not only as the predominant but only ERM protein expressed in hepatocytes and emphasizing its importance in organization and maintenance of the canalicular membrane structure and function." (PMID 37928027, 2023). "Thus, to validate the absence of Ezrin in hepatocytes, we developed a liver-specific Ezrin knockout mouse and examined Ezrin's function extensively in health and cholestasis." (PMID 37928027, 2023).
colitis (2 papers, 2015 to 2021). Inflammation of the colon. "Next, we sought to determine whether T567E ezrin or AcLOK affected the adhesion cascade on MadCAM-1 under shear flow in Rap1-deficient TEM cells derived from LNs of mice developing colitis, including TH17 and TH1 cells." (PMID 26634692, 2015). "Furthermore, we adoptively transferred Rap1-deficient CD4+ pathogenic T cells into the radiated normal mice, and investigated whether the expression of T567E ezrin reduced the development of colitis." (PMID 26634692, 2015).
colorectal adenocarcinoma (2 papers, 2018 to 2021). The most common type of colorectal carcinoma. "Here, we investigated whether PD-L1 expression in human colorectal adenocarcinoma cells (LS180) is affected by ezrin/radixin/moesin (ERM), functioning as scaffold proteins that crosslink plasma membrane proteins with the actin cytoskeleton." (PMID 34577564, 2021). "We initially assessed the gene expression levels of PD-L1, ezrin, radixin, and moesin in LS180 cells and Caco-2 cells which is also a representative human colorectal adenocarcinoma cell line and was used for comparison with LS180 cells." (PMID 34577564, 2021).
COVID-19 (2 papers, 2021 to 2022). A disease caused by infection with severe acute respiratory syndrome coronavirus 2. "By comparing the upregulated genes between COVID-19 patients and recovered individuals, we found that 21 genes (i.e., RPL4, MT-ND2, SCD5, MT-CYB, EZR) were shared between the conditions." (PMID 36059456, 2022). "In addition to inhibiting the key receptors involved in COVID-19, such as ACE2 and the newly suggested TLRs, an Ezrin agonist or molecule that increases Ezrin functionality could be a strategic approach to inhibiting SARS-CoV-2 viral entry." (PMID 33498183, 2021). "Furthermore, targeting TLRs, CLRs, and other receptors (Ezrin and dipeptidyl peptidase-4) that do not directly engage SARS-CoV-2 S protein, but may contribute to augmented anti-viral immunity and viral clearance, may represent therapeutic targets against COVID-19." (PMID 33498183, 2021).
diffuse large B-cell lymphoma (2 papers, 2020 to 2022). "The oncogenic role of Ezrin is not limited to solid tumors as it has also been seen in blood cancers, such as diffuse large B-cell lymphoma, where the knockdown of Ezrin attenuated chemotherapy resistance." (PMID 33240887, 2020).
E. coli infection (2 papers, 2021). "The expression of six genes (KRT18, ARPC5L, ACTG1, ARPC2, EZR, and YWHAZ) related to pathogenic E. coli infection was simultaneously increased with TNFRSF11B overexpression via gene set enrichment analysis (GSEA)." (PMID 34938284, 2021). "In addition, only six genes (KRT18, ARPC5L, ACTG1, ARPC2, EZR, and YWHAZ) related to pathogenic E. coli infection were simultaneously increased in both GSEA studies; these genes are mostly involved in focal adhesion, as determined via GO analysis." (PMID 34938284, 2021).
fibrosarcoma (2 papers, 2024). A malignant mesenchymal fibroblastic neoplasm affecting the soft tissue and bone. "Syndecan 2 directly mediates IGFI-induced extracellular signal-regulated kinase 1/2 (ERK1/2) activation, recruits ezrin, contributes to actin polymerization and ezrin–actin membrane localization, and ultimately facilitates the progression of IGFI-dependent fibrosarcoma cell migration." (PMID 39334952, 2024).
follicular thyroid carcinoma (2 papers, 2019). "We carried out immunohistochemical analysis of ezrin and phospho-ezrin (T567) in patient samples of papillary thyroid carcinoma (PTC), follicular thyroid carcinoma (FTC), follicular variant of papillary thyroid carcinoma (FVPTC) and follicular adenoma (FA)." (PMID 30996241, 2019). "In this study, we found that phosphorylated ezrin is significantly activated by estrogen and more expression was found in invading areas of follicular thyroid carcinoma." (PMID 30996241, 2019). "For disclosing the reason for the extrathyroidal invasion, in vitro experiments were performed in normal thyroid (Nthy-ori3-1) cells as well as in follicular thyroid cancer (FTC-133) cells and observed that estrogen has a key role in inducing the expression of ezrin in both the cell lines." (PMID 30996241, 2019).
gastric adenocarcinoma (2 papers, 2012 to 2024). "EZR mRNA levels are highly expressed, and their expression is associated with biologically relevant molecular processes in cervical squamous carcinoma and stomach adenocarcinoma." (PMID 38972247, 2024). "The positive rate of Ezrin protein expression was significantly higher in gastric adenocarcinoma and dysplasia compared with that in the normal gastric mucosa." (PMID 23039327, 2012). "Ezrin protein expression was examined by immunohistochemistry in 26 normal gastric mucosa, 32 dysplasia, and 277 gastric adenocarcinomas." (PMID 23039327, 2012). "The detection of Ezrin expression can be used as the marker for early diagnosis and prognosis of gastric adenocarcinoma." (PMID 23039327, 2012). "All above data point to the importance of Ezrin not only as a useful marker of early diagnosis and prognosis but also as a potential therapeutic target in gastric adenocarcinoma." (PMID 23039327, 2012). "This study is aimed to investigate the clinicopathological significance of Ezrin overexpression in gastric adenocarcinomas." (PMID 23039327, 2012). "Ezrin protein showed higher positivity in gastric adenocarcinoma (score 1, 79.8%, 221/277; score 2, 60.6%, 168/277) compared with the adjacent normal gastric mucosa (score 1, 19.2%, 5/26; score 2, 0, 0/26)." (PMID 23039327, 2012). "However, Ezrin protein expression level was not correlated with the patient age, gender, histological type status of gastric adenocarcinoma (P>0.05)." (PMID 23039327, 2012).
gastrointestinal stromal tumor (2 papers, 2013 to 2014). "Ezrin overexpression in gastrointestinal stromal tumors was associated with the nongastric location and decreased disease-free survival." (PMID 25580109, 2014).
glomerular diseases (2 papers, 2016 to 2018). "Ezrin seems to be associated with Rac1 activation when glomerular podocytes are injured, and the suppression of ezrin expression might thus be beneficial for protection of proteinuria in glomerulopathies." (PMID 29540766, 2018).
invasive breast carcinoma (2 papers, 2023 to 2025). A carcinoma that infiltrates the breast parenchyma. "We sought, in the current study, to determine the frequency of ezrin mRNA and protein expression in large cohorts of well annotated unselected early‐stage invasive breast cancer patients and determine associations with patient survival." (PMID 36938826, 2023). "In conclusion, this study demonstrates that high ezrin protein expression is associated with shorter patient survival in a large, well‐annotated early‐stage invasive breast cancer patient cohort." (PMID 36938826, 2023).
kidney injury (2 papers, 2024 to 2025). Trauma to the kidney. "Lactate promotes the lactylation of ezrin at K263, whereas the K263 mutation reduces the lactylation of ezrin and attenuates inflammation-mediated kidney injury." (PMID 40584617, 2025).
malaria (2 papers, 2015 to 2017). Malaria is a serious and sometimes fatal disease caused by a parasite that commonly infects a certain type of mosquito which feeds on humans. "On the basis that ezrin likely has a key role in the pathogenesis of malaria, additional anti-malarial compounds were screened to identify novel ezrin inhibitors with better efficacy and drug properties than NSC305787." (PMID 28061797, 2017). "This analysis revealed that the ezrin protein has important roles in various pathways though its function in the regulation of actin cytoskeleton may be the most relevant to malaria." (PMID 25889165, 2015).
metastatic melanoma (2 papers, 2015 to 2018). A melanoma that has spread from its primary site to another anatomic site. "The potent phagocytic activity of tumor cells has been referred to as a determinant of aggressive behavior in metastatic melanoma cells, with proteins such as ezrin being expressed on phagocytic vacuoles." (PMID 26525147, 2015).
myxofibrosarcoma (2 papers, 2012 to 2024). A malignant fibroblastic neoplasm arising from the soft tissue. "The exact upstream mechanism of action of MET in myxofibrosarcomas remains unclear, but it may be related to ezrin." (PMID 22736953, 2012).
pancreatic duct adenocarcinoma (2 papers, 2010 to 2021). "Patients with pancreatic ductal adenocarcinoma (PDAC) with membranous ezrin expression exhibited poorer prognosis compared to those without membranous ezrin expression, and ERM protein was more likely to be present in poorly differentiated cancers." (PMID 20569470, 2010). "The results indicate that ezrin may play an important role in the early development of pancreatic ductal carcinoma." (PMID 20569470, 2010). "Ezrin was also expressed in intercalated ducts adjacent to the adenocarcinoma, which has been considered to be the origin of ducts and acini, as well as the starting point of pancreatic ductal carcinoma development." (PMID 20569470, 2010). "Therefore, the Erk1/2 pathway may also be involved in ezrin-induced cell motility, invasion and morphological changes in pancreatic ductal adenocarcinoma." (PMID 20569470, 2010).
pancreatic insufficiency (2 papers, 2017 to 2022). "Here, we investigated the role of Ezrin in PBD MΦs from CF patients (CF PBD MΦs), each of whom had a classic CF phenotype of chronic lung disease and pancreatic insufficiency, and carried at least one copy of the F508del mutation." (PMID 28883468, 2017).
rheumatoid arthritis (2 papers, 2014 to 2021). A chronic, systemic autoimmune disorder characterized by inflammation in the synovial membranes and articular surfaces. "This study aimed to investigate the role and regulatory mechanisms of Ezrin in synovial vessels in rheumatoid arthritis (RA)." (PMID 34459110, 2021). "Ezrin's effect on enhanced T cell activation through changed expression has already been described in studies on rheumatoid arthritis and humoral immunity." (PMID 24614191, 2014).
schwannoma (2 papers, 2023 to 2025). A benign, usually encapsulated slow growing tumor composed of Schwann cells. "It is now unanimously accepted in the literature that the origin of schwannomas is associated with a mutation in a cytoskeletal protein called Merlin, Neurofibromin 2, or schwannomin, which belongs to the ERM (Ezrin–Radixin–Moesin) protein family and is regulated by the tumor suppressor gene NF2." (PMID 40722574, 2025). "Murine Nf2-mutant schwannoma cells also exhibited striking Nrg1−stimulated ruffling and EIPA-sensitive dextran-488 uptake that was reversed by Nf2 re-expression or ezrin depletion." (PMID 36944680, 2023).
skin carcinoma (2 papers, 2016 to 2022). "Specifically, baicalein (2.5–40 μM) inhibited the migration and invasion of A431 skin carcinoma cells via suppression of Ezrin and phos-Ezrin expression." (PMID 27735841, 2016). "Ezrin is highly expressed in skin cancer, plays an important role in the metastasis of tumors, and was found to be involved in the inhibition of skin carcinoma by baicalein." (PMID 27735841, 2016).
synovial sarcoma (2 papers, 2011 to 2015). "Unexpectedly, all five synovial sarcoma patients were positive for ezrin, correlation that has demonstrated to be statistically significant (Fisher's exact test, P = .03)." (PMID 21785570, 2011).
thymoma (2 papers, 2008 to 2023). A neoplasm arising from the epithelial cells of the thymus. "The ezrin, radixin and moesin proteins, involved in intracellular anchoring of cell membrane proteins to the cytoskeleton, were detected by both the MG-thymoma MS samples and the exon arrays." (PMID 18545673, 2008). "MG-thymoma radixin median exonic change increased but ezrin and moesin decreased, reflecting specific regulation for each member of this protein family." (PMID 18545673, 2008).
acute leukemia (1 paper, 2025). A clonal (malignant) hematopoietic disorder with an acute onset, affecting the bone marrow and the peripheral blood. "Among its components, stathmin 1 (STMN1) and ezrin (EZR) stand out for their significant involvement in the pathogenesis and progression of acute leukemias." (PMID 40982350, 2025). "This review aims to explore the roles of STMN1 and EZR in the pathogenesis of acute leukemias, assessing their potential as therapeutic targets." (PMID 40982350, 2025). "In this review, evidence on the involvement of stathmin 1 (STMN1), a key protein in the regulation of microtubule dynamics, and ezrin (EZR), the plasma membrane-microfilament linker, in the pathogenesis, progression, and response to therapy in acute leukemias is presented." (PMID 40982350, 2025).
anaplastic thyroid carcinoma (1 paper, 2016). "The ezrin gene was up-regulated in established anaplastic thyroid carcinoma cells." (PMID 26818711, 2016).
atypical endometrial hyperplasia (1 paper, 2020). An endometrial hyperplasia characterized by cytologic and architectural changes which may lead to endometrial carcinoma. "Interestingly, increased levels of Ezrin have also been reported in atypical endometrial hyperplasia and uterine endometrioid adenocarcinoma." (PMID 32883230, 2020).
brain tumors (1 paper, 2023). "The cytoskeletal proteins, such as actin, tubulin, fascine, ezrin, and rho-GTPases, are becoming increasingly attractive targets for targeted therapy of brain tumors." (PMID 37556022, 2023).
celiac disease (1 paper, 2016). An autoimmune genetic disorder with an unknown pattern of inheritance that primarily affects the digestive tract. "HSP90AA1, MKKS, EZR, HSPA14, APOB and CAD are proteins that involved in protein networks of celiac disease and have been determined as seeds." (PMID 27895852, 2016).
cervical squamous cancer (1 paper, 2022). "Although the relative mRNA expression level of PD-L1 was low in HCS-2 cell, those of ezrin, radixin, and moesin in HCS-2 cells rank high among human uterine cervical squamous cancer cell lines analyzed." (PMID 35807113, 2022).
chondrosarcoma (1 paper, 2015). A malignant cartilaginous matrix-producing mesenchymal neoplasm arising from the bone and soft tissue. "Supportively, similar effects of Ezrin were also discovered in another system, where fibroblast growth factor induced Ezrin expression resulted in growth arrest in the G1 phase in rat chondrosarcoma cells." (PMID 26202611, 2015).
chordoma (1 paper, 2022). Chordomas are rare malignant tumors arising from embryonic remnants of the notochord in axial skeleton. "Despite the identification of numerous genes with dysregulated expression in vitro or in vivo in chordoma (e.g. brachyury, EGFR, Ezrin, MMP-9, c-MET, FHIT, etc.) conventional or targeted chemotherapeutic agents showed a partial response at best-case scenarios in clinical case-series." (PMID 36033338, 2022).
Cirrhosis (1 paper, 2009). A chronic disorder of the liver in which liver tissue becomes scarred and is partially replaced by regenerative nodules and fibrotic tissue resulting in loss of liver function. "Regarding staining status of ezrin, the HBV-HCC patients with positive ezrin immunoreactivity had smaller tumor size, higher frequency of cirrhosis, tumor de-differentiation, satellite lesions, and vascular invasion." (PMID 19604375, 2009).
deafness (1 paper, 2022). An inherited or acquired condition characterized by the complete loss of the ability to hear from one or both ears. "Indeed, we observed a slight, but significant increase of ezrin expression levels, that was nonetheless insufficient to rescue the deafness in rdx (−/−) mice." (PMID 36518539, 2022).
depression (1 paper, 2023). "At cellular and molecular levels, EA prevents morphological atrophy of astrocytes (which is a leading histopathological hallmark of depression) as well as the decrease in astrocyte-associated ezrin that controls fine morphology of these cells." (PMID 37248211, 2023). "In parallel with preventing the development of depression-like behaviours, treatment with fluoxetine and exposure to EA averted CUMS-induced astrocytic atrophy and CUMS-induced decrease of astrocyte-associated ezrin." (PMID 37248211, 2023).
developmental delay (1 paper, 2025). "Genetic truncation or mutation of the gene encoding band 4.1, ezrin, radixin, and moesin (FERM) domain protein containing 4A (FRMD4A) is associated with brain developmental diseases, including microcephaly with global developmental delay." (PMID 41155374, 2025).
diabetic nephropathy (1 paper, 2015). "Interaction with Nherf2 and ezrin and participation in the PDGFβ signaling axis highlights the possibility of Schip1 involvement in diabetic nephropathy, which should be the course for future functional studies of this protein." (PMID 25807495, 2015).
ductal carcinoma in situ (1 paper, 2025). "We analyzed the localization of HER2, NHERF1, and Ezrin in HER2-positive human ductal carcinoma in situ (DCIS)." (PMID 40390040, 2025).
Dysmenorrhea (1 paper, 2022). Pain during menstruation that interferes with daily activities. "The authors observed that the symptoms’ prevalence such as dysmenorrhea, deep dyspareunia, acyclic pain, and dysuria were also similar between all the three different groups that were immunostaining positive for Ezrin." (PMID 35793608, 2022).